STS (steroid sulfatase)
Description:
Catalyzes the conversion of sulfated steroid precursors, such as dehydroepiandrosterone sulfate (DHEA-S) and estrone sulfate to the free steroid.
Synonyms: ASC; ARSC1; ARSC; ES; SSDD; XLI
Target class: Enzyme; Hydrolase
Chemical probes: CHEMBL3235682, PD084844
Gene: Protein-coding gene on chromosome X (7,147,237 to 7,804,358, forward strand). Ensembl gene ENSG00000101846.
Subcellular location: Cytoplasmic vesicle, secretory vesicle, microneme membrane; Endoplasmic reticulum membrane
Pathways (Reactome):
Metabolism: Glycosphingolipid catabolism; Metabolism of steroid hormones
Metabolism of proteins: The activation of arylsulfatases
Homologues: Orthologues: chimpanzee STS (99% identical), macaque STS (97% identical), dog STS (79% identical), rat Sts (62% identical), tropical clawed frog sts (62% identical), zebrafish sts (58% identical), mouse Sts (34% identical), Drosophila melanogaster CG7402 (24% identical), Drosophila melanogaster CG32191 (24% identical), Caenorhabditis elegans sul-2 (24% identical), Drosophila melanogaster CG7408 (24% identical), Drosophila melanogaster Sulf1 (19% identical), and 3 more. Paralogues in human: ARSL (52% identical), ARSH (51% identical), ARSD (49% identical), ARSF (49% identical), GALNS (31% identical), ARSA (30% identical), ARSG (28% identical), ARSI (24% identical), ARSB (24% identical), ARSJ (24% identical), SULF2 (21% identical), SULF1 (21% identical), and 4 more.
Diseases named in the same sentence as STS in open-access papers:
STS is named in the same sentence as 84 diseases in open-access papers, as found by Europe PMC text mining. Sharing a sentence is not in itself a finding about the gene and the disease. The quoted sentences say what the papers report.
breast carcinoma (38 papers, 2009 to 2025). "Expression of STS protein has been reported in 74% of breast cancers and its expression is significantly associated with larger tumour size, and with an increased risk of recurrence and poorer overall survival." (PMID 28612226, 2017). "Thirdly, STS, the enzyme responsible for the hydrolysis of steroid sulphates to their unconjugated biologically active forms, is overexpressed in breast cancer and is known to be associated with a worse outcome." (PMID 28612226, 2017). "In breast cancer, STS mRNA expression and activity are higher in cancerous compared to normal breast tissue, with elevated STS mRNA expression being significantly associated with lymph node metastasis, histological tumor grade, and poor prognosis." (PMID 26213785, 2015). "Our results are however in contradiction with these observations because EST1E1 was positively associated with CDC47 and STS expression in breast cancer (p < 0.05)." (PMID 21556246, 2009). "Studies in patients with ERalpha-positive breast cancer showed that expression of more active STS isoforms under estrogen therapy may cause upregulation of E2, which would further promote cancer progression." (PMID 23476785, 2013). "Previous research by our group indicated that SGLXD, the original form of mSGLXD, simultaneously downregulated aromatase and steroid sulfatase at transcription and protein levels in ER-positive breast cancer cell lines MCF-7 and T47D, which may underlie the anti-tumor mechanism of SGLXD." (PMID 25405542, 2015). "Clinical development of arylsulfamates targeting human steroid sulfatase (STS) for breast cancer treatment has advanced to phase II clinical trials, with positive outcomes (22, –24)." (PMID 40638084, 2025). "Studies have also shown that inhibition of aromatase can increase the expression and activity of STS in breast cancer." (PMID 37188267, 2023). "Estrogen-3-O-sulfamates (EMATEs) are a class of steroidal compounds, which act as irreversible inhibitors of steroid sulfatase (STS), an enzyme involved in the development of estrogen-dependent breast cancer." (PMID 36838678, 2023). "In breast cancer the first phase 1 clinical trial with an STS inhibitor has been performed in 2003 and 2004." (PMID 37188267, 2023). "SR16157 was a steroid sulfatase inhibitor and also a selective estrogen receptor α modulator, which has been used in clinical trials of breast cancer." (PMID 36545327, 2022). "We present here theadvances achieved in the development of newsulfamoylated 4-(1-phenyl-1H-1,2,3-triazol-4-yl)phenolderivatives as potent steroid sulfatase (STS) inhibitors for the treatmentof breast cancer." (PMID 35235747, 2022). "On the other hand, STX-64 is a first-generation STS inhibitor that showed promising results in the treatment of advanced breast cancer." (PMID 34638451, 2021). "Our results show that quercetin and known breast cancer drugs (ER antagonists, tamoxifen and fulvestrant, and STS inhibitor STX64) significantly inhibit MCF-7 cell proliferation in a concentration-dependent manner." (PMID 36312461, 2019). "Estrogenb-locking drugs developed for treating estrogen-dependent breast cancers include antagonists of estrogen receptors (ERs) and inhibitors of estrogen synthesis enzymes such as aromatase and steroid sulfatase (STS)." (PMID 36312461, 2019). "The implications of our findings on the potential of STS inhibition as a therapeutic approach in breast cancers are also problematic." (PMID 29563635, 2018). "These sulfo-conjugated steroids can be re-converted into active free estrogens in breast cancer tissue via cleavage of the sulfate group by the STS and further conversion by the enzymes 3β-hydroxysteroid dehydrogenase and aromatase in the case of DHEA." (PMID 30186172, 2018). "Expression of STS and other enzymes involved in oestrogen biosynthesis were assessed predominately in primary breast cancer samples." (PMID 28612226, 2017).
breast carcinoma (continued). "We measured the mRNA levels of STS and OATPs in primary breast cancer tissue samples of postmenopausal patients to assess the clinical significance of our model." (PMID 27228187, 2016). "STS expression is under the control of estrogens in breast cancer, and it is down-regulated by GnRH agonists and danazol in endometriotic tissue." (PMID 26924986, 2016). "The prostate cancer cell line LNCaP exhibits higher STS activity than some breast cancer cell lines." (PMID 26213785, 2015). "Others are investigating the potential for dual-acting compounds that target both STS and ERα or STS and aromatase, and second-generation STS inhibitors have been shown to be effective against E2S-stimulated breast cancer in vivo." (PMID 26213785, 2015). "Similar effects of STS were also reported from breast cancer studies, where STS activity correlated with the E2 serum levels." (PMID 25429284, 2014). "For breast cancer diagnosis, STS catalyzing the hydrolysis of steroid sulfates to estrogens is an attractive target, and this is also true for aromatase." (PMID 23476785, 2013). "In breast cancer, the STS pathway with the reduction of E1 to E2 is catalyzed by reductive 17beta-HSDs." (PMID 23476785, 2013). "The constitutive expression of STS gene (steroid sulfatase gene) promotes the growth of human breast cancer cells." (PMID 20126641, 2010). "The enzyme steroid sulfatase (STS) is crucial in regulating estrogen production in breast cancers." (PMID 40689201, 2025). "Proliferation studies showed that, in breast cancer cells treated with this STS inhibitor, the DNA synthesis decreased by a modest 20%, and the estradiol concentration decreased by 26%, suggesting the treatment with STS inhibitors alone was not sufficient to block cancer cells growth." (PMID 36654818, 2022). "Only one of these STS inhibitors (Irosustat) has reached clinical trials (phase II) showing clinical benefits when combined with an aromatase inhibitor, but larger studies are required before to be translating this to a marketed drug to treat breast cancer." (PMID 33924352, 2021). "Regarding STS inhibitors, few clinical trials have been developed, but all of them agree that it is a well-tolerated treatment that can be used in patients with ER + breast cancer." (PMID 34638451, 2021). "Steroid sulfatase can be one of the most efficient targets in the treatment of breast cancer." (PMID 31114446, 2019). "More active expression of STS isoform may occur under estrogen therapy in patients with ERα positive breast cancer." (PMID 31114446, 2019). "Finally, a dual aromatase/STS inhibitor [11C]10 has been 11C-labeled using [11C]CH3I as one of a series of compounds intended for breast cancer imaging." (PMID 28927325, 2017). "Because STS has a postulated significant role in the carcinogenicity of estrogens, STS is considered as a target enzyme for blocking estrogen-mediated carcinogenesis, and potent STS inhibitors have been developed and tested in rodents and in postmenopausal women with breast cancer." (PMID 28977889, 2017). "Steroid sulfatase is the key enzyme involved in hydrolyzing E1S to E1, and its activity is known to directly increase the proliferation of estrogen-dependent breast cancer and endometrial cancer." (PMID 28326039, 2017). "Herein, we demonstrated that activation of steroid sulfatase (STS) and organic anion transporter peptides (OATPs) could make breast cancer cells acquire AI resistance." (PMID 27228187, 2016). "Furthermore, these results are in sharp contrast to other findings that show breast cancer patients have a significantly longer disease-free survival if their STS mRNA levels are low and that STS protein expression correlates with ERα expression." (PMID 26213785, 2015). "Similar to breast cancer, STS activity has been detected in normal and cancerous prostate tissues." (PMID 26213785, 2015). "STS enzyme activity was detected in the great majority of breast carcinomas." (PMID 26240785, 2015).
breast carcinoma (continued). "However, STS activity can be 50–200 times higher than aromatase activity in breast cancer tissue, and STS mRNA is frequently detected in breast tumors, whereas aromatase levels are relatively low." (PMID 26213785, 2015). "Most of the research has focused on STS, and specific inhibition of this enzyme could become an effective therapeutic tool in estrogen dependent breast cancer and possibly in prostate cancer patients." (PMID 24027559, 2013). "Induction of STS transcription by estradiol through binding to ER and via activation of estrogen-response elements in the promoter region results in driving the 1a and 1b transcripts in breast carcinoma." (PMID 23476785, 2013). "Finally we show that tamoxifen and fulvestrant, both GPER agonists, also elevate STS activity indicating that its use in breast cancer patients may have unwanted consequences in the colon." (PMID 28326039, 2017). "Based on biological and clinical observations it was suggested that plasma levels of sulfoconjugated and unconjugated steroid hormones and tissue-specific expression of steroid sulfatase (STS) might play a significant role in breast cancer biology and might regulate the effects of endocrine therapy." (PMID 26240785, 2015). "Also, STS activity has consistently been shown to be elevated in breast cancer tissue." (PMID 26213785, 2015). "In MCF-7 breast cancer cells, E1-3-MTP competitively inhibited STS activity by 52 and >98% at 100 and 10 μM concentrations, respectively." (PMID 32363947, 2020). "Among already available STS inhibitors, the cyclopentane carboxylate derivate STX64 (irosustat) is currently undergoing clinical trials for therapy of prostate, endometrial and breast cancer." (PMID 25429284, 2014). "It is known that the steroid sulfatase (STS) and the estrogen sulfotransferase (EST1E1) are commonly expressed in human breast carcinomas." (PMID 21556246, 2009). "Inhibitors of STS (STX64) and aromatase (anastrozole, letrozole) can block this intracrine formation of estrogens and, therefore, are used for clinical (aromatase inhibitors) or experimental (STS inhibitors) breast cancer therapy." (PMID 30186172, 2018). "Our results suggest that STS and OATP mRNAs may be novel indicators of the need for SERM or SERD treatment of recurrent AI-resistant breast cancers." (PMID 27228187, 2016). "Thus, ERα activation is important in regulating STS activity and subsequent E1 and E2 synthesis, although a full understanding of what regulates STS and SULT1E1 expression and activity in breast cancer remains to be elucidated." (PMID 26213785, 2015). "In vitro and in vivo studies using STS inhibitors imply that the dominant effect of increased STS activity in breast cancer is not inhibition of growth by androgens, but rather estrogen-driven proliferation." (PMID 26213785, 2015). "The non-steroidal STS inhibitor STX64 also referred as Irosustat was the first to enter the clinical phase in postmenopausal women with breast cancer while steroidal inhibitor (E1-3-O-sulfamate, EMATE) together with progestin norethindrone acetate has been studied in endometriosis patients." (PMID 37188267, 2023). "While STS inhibition prevented DHEAS-stimulated growth of MCF-7 breast cancer cells, an effect which was not reproduced by concurrent treatment with aromatase inhibitors, and serum DHEAS have been shown to be significantly higher in women who progressed on an AI." (PMID 28795252, 2017). "The importance of DHEAS as a precursor for androstenediol was shown by its ability to stimulate the proliferation of breast cancer cells, which could be blocked with an anti-oestrogen or STS inhibitor, but not an AI." (PMID 28612226, 2017). "This study provides initial proof-of-concept data that suggest that STS inhibition is capable of reducing tumour proliferation as measured by 18F-FLT-PET in vivo, and in tumour biopsies by changes in Ki-67 in a cohort of previously untreated patients with breast cancer." (PMID 28795252, 2017).
breast carcinoma (continued). "Therefore, if STS and OATP mRNAs are overexpressed in primary breast cancers or recurrent sites, SERM or SERD may effectively treat resistant and recurrent lesions." (PMID 27228187, 2016). "Early studies showed that DHEAS caused proliferation in T47D breast cancer cells, known to have STS activity, even when cotreated with tamoxifen, implying that androgens influence breast cancer proliferation through AR activation and not just through estrogenic metabolites." (PMID 26213785, 2015). "On the other hand, IL6 and tumor necrosis factor (TNF)α increased STS activity in a breast cancer cell line MCF7 not changing the mRNA levels, which suggested posttranslational modifications via STS glycosylation." (PMID 26924986, 2016). "Although circulating DHEAS concentration correlates positively with breast cancer incidence in premenopausal and postmenopausal women, the importance of androgen synthesis through DHEAS desulfation via STS in breast cancer has not yet been fully explored." (PMID 26213785, 2015).
X-linked ichthyosis (21 papers, 2007 to 2026). "Based on the mild phenotypes and high prevalence of common ichthyoses, we suspected that the diagnosis for the two patients was ichthyosis vulgaris caused by FLG mutations or recessive X-linked ichthyosis associated with STS (steroid sulfatase) deletions." (PMID 36332686, 2022). "Background and aims: X-linked ichthyosis (XLI) is a common recessive genetic disease caused by the deletion of steroid sulfatase (STS) in Xp22.31." (PMID 36118896, 2022). "In particular, accumulation of intracellular cholesterol sulfate by STS deficiency leads to a skin disorder with abnormal keratinization called X-linked ichthyosis (XLI)." (PMID 34675221, 2021). "X-linked ichthyosis (XLI) is a rare X-linked dermatological condition arising from deficiency for the enzyme steroid sulfatase (STS)." (PMID 30768640, 2019). "X-linked ichthyosis (XLI) is a recessive keratinization condition caused by deficient activity of steroid-sulfatase due to mutations in steroid sulfatase (STS) gene located on the X chromosome." (PMID 30021537, 2018). "X-linked ichthyosis is a dermatological condition caused by deficiency for the enzyme steroid sulfatase." (PMID 28934990, 2017). "We first reported the IVCM characteristics of PDCD associated with X-linked ichthyosis, which was caused by a deletion of the steroid sulfatase (STS) gene, confirmed by gene analysis." (PMID 28302098, 2017). "X-linked ichthyosis (XLI) is a rare dermatological condition arising from deficiency for the enzyme steroid sulfatase (STS)." (PMID 27711218, 2016). "X-linked ichthyosis (XLI) is a dermatological condition arising from a deficiency for the enzyme steroid sulfatase (STS)." (PMID 27711218, 2016). "The loss of STS activity due to STS gene deletion or point mutations results in X-linked ichthyosis, a genetic skin disorder that affects 1 in 2000 to 1 in 6000 males and is characterized by typical scaling of the skin epidermis." (PMID 26924986, 2016). "STS deletion is associated with X-linked ichthyosis (XLI) in male due to deficiency of steroid sulfatase (STS) activity." (PMID 22487416, 2012). "Deletions spanning the STS (steroid sulfatase) gene at Xp22.31 are associated with X-linked ichthyosis, corneal opacities, testicular maldescent, cardiac arrhythmia, and higher rates of developmental and mood disorders/traits, possibly related to the smaller volume of some basal ganglia structures." (PMID 32766777, 2020). "Additional samples were collected from the forearms of subjects with ichthyosis vulgaris (filaggrin (FLG) deficiency), recessive X-linked ichthyosis (steroid sulfatase (STS) deficiency) and autosomal recessive congenital ichthyosis type lamellar ichthyosis (transglutaminase 1 (TGM1) deficiency)." (PMID 24130705, 2013). "STS encodes steroid sulfatase, deficiency of which causes X-linked ichthyosis." (PMID 17517138, 2007). "Deletions or mutations of the Xp22.31 locus are associated with X-linked ichthyosis (OMIM 308100, XLI), which is a dermatologic disorder with characteristic dry and scaly skin due to a deficiency of the enzyme steroid sulfatase." (PMID 33509128, 2021). "X-linked ichthyosis (XLI, OMIM#308100) is one of the second most prevalent type of ichthyosis caused by steroid sulfatase (STS) deficiency due to mutation of STS gene located on the X chromosome, affecting approximately 1:2000 to 1:6000 males worldwide." (PMID 30021537, 2018). "An inverse pathomechanism takes place in recessive X-linked ichthyosis (XLI, MIM 308100) in which deletions in the steroid sulfatase (STS) gene result in insufficiency of the enzyme and SC retention." (PMID 25378284, 2015). "Possibly the most well-known condition relates to the scaling of the skin in patients with recessive X-linked ichthyosis (RXLI) disorder, characterised by a deficiency of steroid sulfatase (STS) resulting in an excess of CholS at the tissue level that can reach up to 12.5% of total lipids." (PMID 40559338, 2025).